SIRT3 (sirtuin 3)
Diseases named in the same sentence as SIRT3 in open-access papers (continued):
Sharing a sentence is not in itself a finding about the gene and the disease.
pulmonary fibrosis (continued). "Previous studies have shown that Sirt3Tg mice, as compared to controls, demonstrate a global ~4-fold increase in SIRT3 expression in all cell types vs. WT mice at baseline and following bleomycin exposure and have reduced bleomycin-induced pulmonary fibrosis." (PMID 34202229, 2021). "Collectively, these studies firmly support that SIRT3 overexpression can mitigate pulmonary fibrosis following asbestos exposure in a manner comparable to that seen following bleomycin exposure." (PMID 34202229, 2021). "A major finding in this study is that Sirt3Tg mice, which globally overexpress SIRT3, have reduced pulmonary fibrosis as compared to WT mice 21 d following asbestos exposure." (PMID 34202229, 2021). "A pharmaceutical compound known as Hexafluoro showed to induce the expression of SIRT3 in mice treated with bleomycin, lessening the development of lung fibrosis by reducing the expression of collagen 1, a-SMA and fibronectin through TGF-B1 inhibition." (PMID 31963720, 2020). "Lungs from idiopathic pulmonary fibrosis patients show decreased SIRT3 activity, as indicated by acetylated mitochondrial SOD (MnSOD) levels, particularly in the lung epithelium." (PMID 32308644, 2020). "There is increasing evidence that Sirt3 plays an important role in the process of lung fibrosis, and it is closely related to inflammation, oxidative stress, apoptosis, autophagy, and ER stress." (PMID 32089781, 2020). "Sirt3 deletion promotes lung fibrosis by augmenting mitochondrial DNA (mtDNA) damage and apoptosis in mouse alveolar epithelial cells and myofibroblasts." (PMID 32308644, 2020). "Additional studies are necessary to better define the role of mtDNA integrity in mediating the beneficial effects of SIRT3 as well as the translational significance in humans, including pulmonary fibrosis." (PMID 26370974, 2015). "We reason that the OGG1/ACO-2/SIRT3/mtDNA axis is important in regulating complex cell signaling that promotes pulmonary fibrosis as well as other degenerative disease of the lungs and tumor development." (PMID 26370974, 2015). "Importantly, treatment with nicotinamide riboside was found to suppress the activation of pulmonary fibroblasts and protect mice from bleomycin-induced pulmonary fibrosis by activating SIRT3." (PMID 41797045, 2026). "Notably, the deacetylation of SOD2 is predicted to be a major mechanism through which SIRT3 reduces mitochondrial DNA damage and apoptosis in lung fibrosis." (PMID 41502422, 2025). "Therefore, targeting SIRT3 to preserve mtDNA presents a promising therapeutic approach for patients with idiopathic pulmonary fibrosis and other forms of pulmonary fibrosis." (PMID 40799515, 2025). "Moreover, this study is the first to propose the PGC1-alpha/Sirt3 pathway as a novel drug target for the treatment of pulmonary fibrosis by inhibiting fibroblast senescence." (PMID 39062010, 2024). "In addition to Sirt3, other members of the sirtuin family, such as Sirt1 and Sirt6, have demonstrated anti-pulmonary fibrosis effects through the inhibition of cellular senescence." (PMID 39062010, 2024). "Our results suggest that hirudin may be a therapeutic agent for pulmonary fibrosis, and we propose that the PGC1-alpha/Sirt3 pathway may be a potential therapeutic target for pulmonary fibrosis." (PMID 39062010, 2024). "Other studies have shown that the mechanism of baicalin’s inhibitory effect on pulmonary fibrosis may inhibit the TGF-β1/Smad signaling pathway by promoting the expression of recombinant Sirtuin 3 (Sirt3) in vivo." (PMID 38666911, 2024). "In conclusion, the anti-fibrotic effect of hirudin on pulmonary fibrosis may be related to the activation of the PGC1-alpha/Sirt3 pathway and its role in anti-fibroblast senescence." (PMID 39062010, 2024). "Sirt3 dysregulation was reported to be involved in the pathological process of lung fibrosis." (PMID 36815239, 2023).
pulmonary fibrosis (continued). "Furthermore, SIRT3 deficiency enhances SMAD3 expression and activates fibroblasts to transition into myofibroblasts, making SIRT3 KO mice more susceptible to pulmonary fibrosis (PF) than WT mice." (PMID 37237500, 2023). "Current evidence has demonstrated that SIRT3 dysregulation promotes pulmonary fibrosis." (PMID 37196115, 2023). "Besides SIRT1 and SIRT3, SIRT7 has additionally been recently proposed as a novel regulator of lung fibrosis, and directly implicated in SSc-ILD." (PMID 35268452, 2022). "As far as lung fibrosis is concerned, serum SIRT3 levels were found to be decreased in SSc patients diagnosed with ILD on HRCT scans of the chest (median 0.27 ng/mL, IQR 0.20–0.57 ng/mL) compared to those without ILD (median 0.47 ng/mL, IQR 0.32–0.86 ng/mL; p = 0.005)." (PMID 35268452, 2022). "Strikingly, SIRT3 knock-out mice have been reported to present an exaggerated profibrotic response to bleomycin, whereas transgenic mice with whole body SIRT3 overexpression were found to be protected from bleomycin-induced lung fibrosis." (PMID 35268452, 2022). "Also, SIRT3 mediated fibroblasts-derived extracellular vesicle-induced epithelial cell senescence in pulmonary fibrosis." (PMID 36193088, 2022). "We determined whether whole body transgenic SIRT3 overexpression (Sirt3Tg) protects mice from asbestos-induced pulmonary fibrosis by mitigating lung mtDNA damage and Mo-AM recruitment." (PMID 34202229, 2021). "Among these Sirtuins, Sirt1, Sirt3, Sirt6, and Sirt7 have been well studied in pulmonary fibrosis." (PMID 34925016, 2021). "It will be of considerable interest to determine whether conditional SIRT3 overexpression in AECs, fibroblasts, and/or macrophages is required for mitigating pulmonary fibrosis." (PMID 34202229, 2021). "To determine whether overexpression of SIRT3 mitigates asbestos-induced pulmonary fibrosis, we assessed lung fibrosis in Sirt3Tg as compared to their wild-type (WT) controls." (PMID 34202229, 2021). "A second mechanism that we explored was whether SIRT3 overexpression mitigates lung fibrosis by reducing the recruitment of profibrotic Mo-AMs." (PMID 34202229, 2021). "A second mechanism that we explored in our in vivo lung fibrosis model is whether SIRT3 diminishes recruitment of pro-fibrotic Mo-AMs." (PMID 34202229, 2021). "Our group has established a causal role for the recruitment of pro-fibrotic monocyte-derived alveolar macrophages (Mo-AMs) in the development of both bleomycin- and asbestos-induced lung fibrosis, but the role of SIRT3 in modulating recruitment of Mo-AMs is unclear." (PMID 34202229, 2021). "Sirtuin 3 (SIRT3) is a mitochondrial protein deacetylase regulator of antioxidant response and mitochondrial homeostasis, known to be an age-related pathogenic mechanism in heart and lung fibrosis." (PMID 31011486, 2019). "Finally, it will be of interest to determine whether SIRT3 impacts mtDNA release from various cells involved in lung fibrosis and how mtDNA signaling may alter lung repair and immune responses in health, disease/fibrosis, and aging." (PMID 34202229, 2021). "Collectively, these findings support the anti-aging role of SIRT3 in mitigating pulmonary fibrosis in part by maintaining AT2 cell mtDNA integrity that may be necessary for preserving the "stem" cell role of AT2 cells in the setting of fibrogenic stimuli (i.e., asbestos)." (PMID 34202229, 2021). "Notably, they propose that enhanced expression of SIRT3, a mitochondrial protein deacetylase and regulator of antioxidant response and mitochondrial homeostasis, may reduce cardiac and pulmonary fibrosis in aging." (PMID 31011489, 2019). "Cryptotanshinone has been suggested to be an effective treatment for pulmonary fibrosis, as it modulates the TGF-β1/Smad3, STAT3, and SIRT3 pathways." (PMID 37483618, 2023).
pulmonary fibrosis (continued). "Collectively, these data suggest that SIRT3 overexpression can diminish lung and AEC mtDNA damage following exposure to agents that induce lung fibrosis, such as asbestos or bleomycin." (PMID 34202229, 2021). "Collectively, these data support an important role for SIRT3-dependent preservation of AEC mtDNA as a novel therapeutic focus for managing patients with IPF and other types of pulmonary fibrosis." (PMID 34202229, 2021). "First, we investigated whether SIRT3 can attenuate mtDNA damage in asbestos-exposed murine lungs as well as cultured AECs because mtDNA damage is prominently implicated in mediating AEC mitochondria-regulated (intrinsic) apoptosis that can drive aging and lung fibrosis." (PMID 34202229, 2021). "We reason that SIRT3 preservation of AEC mtDNA is a novel therapeutic focus for managing patients with IPF and other types of pulmonary fibrosis." (PMID 34202229, 2021). "Furthermore, from a clinical perspective, targeting the PGC1-alpha/Sirt3 pathway may enable the development of innovative therapeutic strategies for the treatment of pulmonary fibrosis, which could help address the critical medical need for pulmonary fibrosis therapy." (PMID 39062010, 2024). "In exploring the specific mechanism by which hirudin exerts anti-oxidative stress and inhibits fibroblast senescence to exert anti-pulmonary fibrosis effects, we found that hirudin promoted the expression of PGC1-alpha and Sirt3 in the lung tissues of mice with pulmonary fibrosis and fibroblasts." (PMID 39062010, 2024). "Baicalein preserved the BLM-induced downregulation of lung Sirt3 expression, and thus the suppression of TGF-β1/Smad signalling pathway and lung fibrosis, which might provide an experimental basis for treatment of IPF." (PMID 36815239, 2023). "In mouse models of pulmonary fibrosis and human lung fibroblasts, a reduction in SIRT3 promotes the acetylation (inactivation) of oxidative stress response regulators and FMD, while SIRT3 overexpression weakens TGFβ1-mediated FMD and significantly reduces the levels of SMAD3." (PMID 37196115, 2023). "Nevertheless, it was also found that Sirt3 expression was significantly decreased in the lung tissues of BLM-treated mice and Sirt3 downregulation contributed to the pathological process of BLM-mediated pulmonary fibrosis." (PMID 36815239, 2023). "In contrast, transgenic mice with systemic SIRT3 overexpression were not affected by bleomycin-induced mtDNA damage and pulmonary fibrosis." (PMID 37196115, 2023). "In addition to pulmonary fibrosis, SIRT1 and SIRT3 deregulation appears to also contribute to skin fibrosis." (PMID 35268452, 2022). "Given the important role of AEC mtDNA damage in promoting mitochondria-regulated apoptosis and subsequent pulmonary fibrosis, we reason that strategies aimed at augmenting lung SIRT3 levels are an innovative therapeutic target for managing patients with IPF and other forms of lung fibrosis." (PMID 34202229, 2021). "The precise mechanism(s) by which SIRT3 overexpression mitigates lung fibrosis is not fully established from these studies; however, we investigated two possibilities: (i) reducing mtDNA damage and (ii) ameliorating lung recruitment of fibrogenic Mo-AMs." (PMID 34202229, 2021). "However, the therapeutic potential of targeting pathways such as activation of SIRT3 via the TGF-β/Smad3 pathway offer exciting new avenues to combating cardiac and pulmonary fibrosis." (PMID 31011486, 2019). "It was also found that baicalein markedly increased sirtuin 3 (Sirt3) expression in the lung tissue of BLM-treated mice, which may contribute to the inhibitory effects of baicalein against BLM-induced lung fibroblast senescence and pulmonary fibrosis." (PMID 36815239, 2023). "Furthermore, baicalein preserved the BLM-induced downregulation of lung Sirt3 expression, and thus the suppression of TGF-β1/Smad signalling pathway and lung fibrosis, which might provide an experimental basis for treatment of IPF." (PMID 36815239, 2023).
pulmonary fibrosis (continued). "Bleomycin-induced lung fibrosis reduces lung SIRT3 and OGG1 expression in WT but not Sirt3Tg mice." (PMID 34202229, 2021). "Third, overexpression of SIRT3 using either genetic or pharmacologic approaches mitigates oxidant-induced fibroblast profibrotic signaling and AEC mtDNA damage and apoptosis in vitro as well as bleomycin-induced lung fibrosis in vivo and promotes lung fibrosis resolution in aged mice." (PMID 34202229, 2021).
osteoporosis (24 papers, 2015 to 2026). A condition of reduced bone mass, with decreased cortical thickness and a decrease in the number and size of the trabeculae of cancellous bone (but normal chemical composition), resulting in increased fracture incidence. "The present findings revealed that osteoporosis is associated with the overexpression of miR‐125b‐5p and alteration in the SIRT3/AMPK/mTOR axis, which is followed by the suppression of autophagy in BMSCs and bone tissue." (PMID 40104207, 2025). "For example, SIRT3 overexpression in adeno-associated viral vectors in SAMP6 mice (a model of senile osteoporosis (SOP)) showed that SIRT3 regulates advanced glycation end product (AGE)-induced SOP by modulating mitochondrial autophagy." (PMID 38192409, 2023). "Among these investigations, there is a predominant emphasis on SIRT1 and its association with osteoporosis, followed by attention toward SIRT3 and SIRT6." (PMID 38264287, 2023). "Though recent evidence indicates that SIRT3 is linked to osteoporosis, the exact mechanism is still unclear." (PMID 35692409, 2022). "More importantly, SIRT3 deficiency could contribute to the impaired osteoblast function, bone loss and osteoporosis in SIRT3−/− mice." (PMID 35692409, 2022). "In addition to aging and sex steroid-related bone loss, SIRT3 also takes part in the pathogenesis of ionizing radiation exposure-induced osteoporosis." (PMID 35692409, 2022). "Moreover, Sirt3 also was implicated in a variety of age-related pathologies, such as cardiovascular diseases, osteoporosis, osteoarthritis, metabolic syndrome and neurodegenerative diseases." (PMID 36499074, 2022). "Therefore, in addition to aging models, the researchers also constructed estrogen deficiency-related animal models to study the role of SIRT3 in osteoporosis." (PMID 35692409, 2022). "In addition to age- or sex steroid deficiency-associated bone loss, Sirt3 might also contribute to increased bone resorption in the pathogenesis of osteoporosis caused by IR exposure." (PMID 35054859, 2022). "We show herein that deletion of Sirt3 or pharmacologic inhibition of Sirt3 in mice impairs osteoclast mitochondrial function and prevents the increased bone resorption and loss of bone mass caused by the 2 most important causes of osteoporosis in humans — aging and estrogen deficiency." (PMID 33878033, 2021). "SIRT3 can reduce mitochondrial oxidative stress and mtDNA damage in osteoblasts in vitro, and SIRT3 knockout mice exhibit early‐stage osteoporosis." (PMID 40681473, 2025). "In conclusion, our findings demonstrate that mitochondrial deacetylase SIRT3 is a key regulator of excessive bone resorption induced by IR exposure, mirroring mechanisms observed in osteoporosis pathogenesis." (PMID 40584154, 2025). "Abnormal expression of Sirt3 is closely related to bone metabolism disorders, so silencing Sirt3 expression can effectively prevent AGEs-induced osteoporosis." (PMID 37038234, 2023). "Overall, it is crucial to further investigate the age- and sex-dependent dual effects exerted by Sirt3 on osteoporosis." (PMID 38264287, 2023). "In the current review, we elaborated on the physiological functions of SIRT3, the cell types involved in bone remodeling, and the role of SIRT3 in osteoporosis." (PMID 35692409, 2022). "Next, we will explain how SIRT3 participates in bone remodeling and osteoporosis from different aspects, including the senescence and differentiation of BMSCs, differentiation of osteoblasts, osteoclastogenesis, and changes in bone mass." (PMID 35692409, 2022). "IR also increased the expression and enzymatic activity of mitochondrial deacetylase Sirtuin-3 (Sirt3)—an essential protein for osteoclast mitochondrial activity and bone resorption in the development of osteoporosis." (PMID 35054859, 2022). "In this review, we are devoted to explaining the role and molecular mechanism of SIRT3 in osteoporosis." (PMID 35692409, 2022).